SINHCAF (SIN3-HDAC complex associated factor)
Description:
Subunit of the Sin3 deacetylase complex (Sin3/HDAC), this subunit is important for the repression of genes encoding components of the TGF-beta signaling pathway. Core component of a SIN3A complex (composed of at least SINHCAF, SIN3A, HDAC1, SAP30, RBBP4, OGT and TET1) present in embryonic stem (ES) cells. Promotes the stability of SIN3A and its presence on chromatin and is essential for maintaining the potential of ES cells to proliferate rapidly, while ensuring a short G1-phase of the cell cycle, thereby preventing premature lineage priming (By similarity).
Synonyms: C12orf14; FAM60A; L4; TERA
Tractability: PROTAC: ubiquitination databases record sites on it.
Gene: Protein-coding gene on chromosome 12 (31,280,584 to 31,327,058, reverse strand). Ensembl gene ENSG00000139146.
Subcellular location: Nucleus
Subcellular location (Human Protein Atlas): Nucleoplasm; Cytosol
Gene Ontology:
Molecular function: protein binding
Biological process: negative regulation of cell migration; negative regulation of cell differentiation; negative regulation of stem cell population maintenance; negative regulation of transcription by RNA polymerase II; negative regulation of transforming growth factor beta receptor signaling pathway; positive regulation of cell population proliferation; positive regulation of stem cell population maintenance
Cellular component: Sin3-type complex; nucleus
Genetic constraint (gnomAD): Loss-of-function variants: 3 observed, 18.74 expected, observed/expected ratio (o/e) 0.16, 90% interval 0.072 to 0.41. The upper end of that interval is the gene's LOEUF score, 0.41, which puts it in group 1 of 6, group 1 being the genes least tolerant of losing a copy. Missense variants: 106 observed, 214.57 expected, observed/expected ratio (o/e) 0.49, 90% interval 0.42 to 0.58. Synonymous variants: 58 observed, 69.32 expected, observed/expected ratio (o/e) 0.84, 90% interval 0.68 to 1.04.
Homologues: Orthologues: dog SINHCAF (100% identical), mouse Sinhcaf (98% identical), guinea pig SINHCAF (97% identical), rat Sinhcaf (97% identical), rabbit SINHCAF (95% identical), macaque SINHCAF (81% identical), zebrafish sinhcaf (77% identical), Drosophila melanogaster CG44774 (48% identical), tropical clawed frog sinhcaf (40% identical).
Diseases named in the same sentence as SINHCAF in open-access papers:
SINHCAF is named in the same sentence as 21 diseases in open-access papers, as found by Europe PMC text mining. Sharing a sentence is not in itself a finding about the gene and the disease. The quoted sentences say what the papers report.
esophageal adenocarcinoma (1 paper, 2021). A malignant tumor with glandular differentiation arising predominantly from Barrett mucosa in the lower third of the esophagus. "Transcriptomics showed that the combination of SLC26A9 and the other four genes, SINHCAF, MICB, KRT19, and MT1X, became a gene signature that predicts the overall survival of esophageal adenocarcinoma." (PMID 35008199, 2021).
type II diabetes (1 paper, 2018). "Despite limited knowledge on SINHCAF function, a recent study identified a single-nucleotide polymorphism present on SINHCAF which is associated with type II diabetes in a cohort of Japanese patients." (PMID 29784889, 2018).
SINHCAF also shares sentences with these, for which no sentence is quoted: tumor (4 papers); cancer (3); esophageal cancer (2); pancreatic cancer (2); embryonic carcinoma (1); esophageal tumor (1); gastric cancer (1); hepatocellular carcinoma (1); infection (1); liver cancer (1); lung carcinoma (1); lymph node metastasis (1); metabolic disease (1); metastatic disease (1); nutritional deficiency (1); osteosarcoma (1); sarcoma (1); urological disease (1); ZIKV infection (1).